EGFR (epidermal growth factor receptor)
Diseases named in the same sentence as EGFR in open-access papers (continued):
Sharing a sentence is not in itself a finding about the gene and the disease.
breast carcinoma (continued). "ErbB2, a member of the human epidermal growth factor receptor (HER/EGFR/ERBB) family, has been reported to be closely related to the occurrence and development of breast cancer." (PMID 29482638, 2018). "In this study, we showed that CD44+/CD24–/low BCSCs enriched from HER2-negative breast cancer cells displayed a radioresistant phenotype with HER2 and EGFR overexpression." (PMID 29464036, 2018). "HER2, a family member of the ERBB transmembrane receptor tyrosine kinases (ERBB1-4 or also known as EGFR and HER2-4) is a well-known target in HER2-amplified breast cancer therapy for both primary tumors and metastases." (PMID 30515368, 2018). "An additional report implicated high levels of heparanase in resistance of metastatic breast cancer models to the small-molecule tyrosine kinase inhibitor of HER2 and EGFR, lapatinib, through the activation of a compensatory EGFR-dependent pathway." (PMID 30413079, 2018). "Interestingly, also in breast cancer, fewer CTCs have been reported for brain metastatic patients when analyzed by the CellSearch system, and those CTCs that were competent to colonize the brain as a distant target organ site were predominantly EpCAM-negative but EGFR, NOTCH1 and HPSE-positive." (PMID 30572662, 2018). "In this study, TGF‐β is positively correlated with EGFR expression in breast cancer tissues, and a functional linkage is observed between TGF‐β signaling and EGFR transactivation in breast cancer cell lines." (PMID 29215776, 2018). "Furthermore, HCRP1 could inhibit breast cancer metastasis by suppressing EGFR phosphorylation." (PMID 30518879, 2018). "EGFR expression in the selected GBM cancer cell lines and the breast cancer cell line, MCF7, was confirmed by Western blot (WB)." (PMID 29313975, 2018). "TGF-β-elicited EMT program augments expression of RTKs such as EGFR and IGF-1R which form cytoplasmic complexes with ER-α and Src leading to anti-estrogen resistance in breast cancer." (PMID 29455658, 2018). "Overexpression of epidermal growth factor receptor (EGFR) has been shown to be an important predictor of early recurrence and death in breast cancer." (PMID 30367629, 2018). "We have shown that, in breast cancer cellular models, JAM-A levels correlate directly with HER2 and EGFR expression, phosphorylation of Akt, and viability of cells with resistance to anti-HER2 therapy." (PMID 30458861, 2018). "We believe our findings lay a framework for an immune-mediated strategy for treating aggressive breast cancer subtypes (TNBC and HER2+ breast cancer), by co-administration of Ad-HER3 with HER2-targeted or EGFR-targeted therapies." (PMID 30092835, 2018). "A strong correlation between EGFR expression and CD163+ macrophages were found in tamoxifen-resistant breast cancer patients." (PMID 29455658, 2018). "In this study, we showed that inhibition of EGFR and ErbB2 decreased the amplitude of SOCE in breast cancer cell lines (SK-BR-3 cells) and in other cancer or proliferating cells." (PMID 29662626, 2018). "Although several mechanisms have been discovered by which Gβγ activates ERK1/2, the transactivation of EGFR pathway appears to be widely explored and accepted; the same has been demonstrated for GPER in breast cancer cells." (PMID 29360846, 2018). "There are two important biological targets related to breast cancer: Human Epidermal Growth Factor Receptor 2 (HER-2) and Epidermal Growth Factor Receptor (EGFR)." (PMID 30477154, 2018). "We began by evaluating the colocalization of MUC1 and EGFR with EEA1, a marker of the early endosome in both BT20 and MDA-MB-468 breast cancer cells." (PMID 29464085, 2018). "With respect to tumors other than breast cancer, GBP1 is considered to act as tumor suppressor gene in colorectal cancer, and as an effector of EGFR-driven tumor cell invasion in glioblastomas." (PMID 29350274, 2018). "Overexpression of EGFR, HER2 and HER3 occurs in 30–40%, 20–30% and ~ 20% of breast cancer cases, respectively." (PMID 29490608, 2018).
breast carcinoma (continued). "Immunoblot analyses revealed that BRC-31 breast cancer cells retained expression of EGFR, N-cadherin, fibronectin (FN) and vimentin at higher levels relative to BRC-32, 36 and 196 breast cancer cells." (PMID 29382358, 2018). "EGFR-targeted agents include small molecule receptor tyrosine kinase inhibitors (RTKIs) and monoclonal antibodies licenced for treatment of NSCLC, breast cancer and colorectal cancer." (PMID 30326612, 2018). "Basal-like breast cancers are characterized by ER−, PR−, HER2−, cytokeratin 5/6 (CK5/6)+ and expression of epidermal growth factor receptor (EGFR)." (PMID 29484537, 2018). "We recently showed that progesterone decreases the activation of multiple kinases like EGFR, AKT1, and ERK1/2 in breast cancer cells, leading to suppression of cell migration." (PMID 30337371, 2018). "EGFR is also essential for the TGF‐β‐induced enhancement of the migration and invasion abilities of breast cancer cells." (PMID 29215776, 2018). "Using Affymetrix expression data from 29 lung and 22 breast carcinoma brain metastases, we again were unable to find a correlation between CXCR4 and EGFR expression." (PMID 29721166, 2018). "In Her2 amplified breast cancer cells, the phosphorylation of PTPIP51 at Tyr176 is to a great extend performed by the EGFR." (PMID 30360441, 2018). "EGFR, HER2 and HER3 are overexpressed in 30–40%, 20–30% and ~20% of breast cancer cases, respectively." (PMID 30241301, 2018). "The examples of successful application of anti-ErbB antibodies in cancer treatment includecetuximab (anti-EGFR) in head and neck cancer therapy andtrastuzumab (anti-HER2) in breast cancer treatment." (PMID 30430004, 2018). "Used in treatment-naïve, ER+/EGFR+/HER2+ breast cancer patients and patients with HER2-positive advanced breast cancer that has progressed after previous treatment to Trastuzumab, anthracycline and taxane derived drugs." (PMID 29732012, 2018). "The data demonstrate that GPR119 agonist inhibits autophagosome formation in cancer cells treated with EGFR-TKI and possess anticancer effects against breast cancer." (PMID 30497501, 2018). "Correlation between miR-125a and miR-125b and EGFR family proteins (EGFR, HER2 and HER3) in HER2 positive breast cancer patients." (PMID 30068375, 2018). "Neratinib, an dual inhibitor of EGFR and HER2, was approved to prescribe in breast cancers by FDA in 2017." (PMID 29455646, 2018). "In this review, we deal with EGFR, VEGFR, PDGFR and FGFR signaling in breast cancer progression, maintenance of cancer stem cell phenotype, tumor-stroma interaction and drug resistance." (PMID 29455658, 2018). "Regarding breast cancer invasiveness, previous studies showed that in ER-negative breast cancer cells or CAFs, E2/GPER signaling induced cell migration through EGFR-dependent activation of connective tissue growth factor (CTGF)." (PMID 29996493, 2018). "It was recently reported that the combined inhibition of EGFR/ErbB2 (via lapatinib) and c-ABL (via imatinib) in fulvestrant-resistant breast cancer cells significantly inhibited cell growth and autophagy." (PMID 30214383, 2018). "A central role of upregulated EGFR/ErbB and the sustained activation of the EGFR/ErbB/ERK signaling pathway has been strongly indicated in the maintenance of antiestrogen-resistant breast cancer cell growth." (PMID 30103729, 2018). "Chromatin immunoprecipitation (ChIP) assay showed that IRIS protein is bound to EGFR and EMS1 (c-Src promote is now under investigation) promoters in breast cancer cells and enhances their transcription (unpublished)." (PMID 28052035, 2017). "In our previous study at our laboratory, it was shown that FUT4 and its regulated LeY sugar chains were significantly up-regulated in NSCLC and breast cancer and promoted EMT induction through EGFR and PI3K/Akt-GSK3β activation." (PMID 28423676, 2017).
breast carcinoma (continued). "This is consistent with the observation that nearly all breast cancers express HER2, but DDAs are only toxic to the lines that exhibit dramatic HER2 or EGFR overexpression." (PMID 28423644, 2017). "Targeted therapies directed against the key members of the growth factor receptor network (GFRN), such as EGFR, PI3K, AKT, and mTOR inhibitors, are currently in preclinical development, clinical trials, or approved for use in breast cancer." (PMID 28446242, 2017). "Previous reports demonstrated that FRK suppresses cell proliferation in breast cancer by various mechanisms, which include the stabilization of PTEN and BRCA1 and the internalization of EGFR." (PMID 29348886, 2017). "Following CNR2 activation, we observed inhibition of breast cancer growth, suppression of EGF/EGFR as well as IGF-I/IGF-IR signaling pathways and their related tumorigenic events in vitro and in vivo." (PMID 27213582, 2017). "The epidermal growth factor receptor (EGFR) and MET receptor are highly expressed in multiple TNBC subtypes with EGFR overexpression in 54% of basal breast cancers (predominantly TNBC)." (PMID 28852500, 2017). "Although Ge had been widely used in EGFR+ NSCLC patients, unfortunately, it demonstrated little effectiveness in treating breast cancer." (PMID 28531218, 2017). "II.Doxorubicin, the current front-line therapy for breast cancer, not only activated MAPK pathway as carmustine, but also up-regulated EGFR/PKC pathway." (PMID 29322918, 2017). "Several previous studies have suggested that, in breast cancer cells overexpressing ErbB2/HER2, it localizes to membrane ruffles or protrusions together with its signaling partners, ErbB1/EGFR and ErbB3/HER3." (PMID 28369073, 2017). "In both breast and pancreatic cancer cells, RAC1 is a downstream effector of ERBB receptors and mediates migratory responses by ERBB1/EGF receptor (EGFR) ligands such as EGF or TGF-α and in breast cancer cells also by ERBB3 ligands such as heregulins." (PMID 28499439, 2017). "We assessed EGFR and EYA2 expression by immunohistochemical staining (IHC) and miR-338-3p expression by miRNA in situ hybridization (MISH) in 95 human breast cancer samples." (PMID 28703807, 2017). "Cell proliferation assays revealed that EGFR overexpression or miR-338-3p inhibition increased breast cancer cell growth, while EYA2 knockdown decreased breast cancer cell growth." (PMID 28703807, 2017). "To study the importance of matrix effectors in ERα-positive breast cancer cell behavior, we first examined the effect of ERα/IGF-IR/EGFR cross-talk on the gene expression of certain MMPs and TIMPs in MCF-7 cells." (PMID 28079144, 2017). "We investigated the relationship between EGFR and/or HER2 dimerization and breast cancer aggressiveness." (PMID 28881584, 2017). "Inactivation of p90RSK3 acts synergistically with EGFR-inhibition, thus posing a potential synthetic lethal drug target for overcoming PI3K-inhibitor resistance in breast cancer." (PMID 28423600, 2017). "Many EGFR inhibitors have been developed and approved by the FDA, such as lapatinib, which has been applied for the treatment of breast cancer." (PMID 28630865, 2017). "Lapatinib (C), a 6-heteroaryl substituted 4-anilinoquinazoline derivative, on the other hand, is an oral dual TK inhibitor that targets both EGFR and HER2 to inhibit the proliferation of breast cancer cells." (PMID 29156606, 2017). "Lapatinib, which is clinically available for patients with breast cancer, is a small molecule that inhibits the tyrosine kinase activities of HER2 and EGFR." (PMID 29140271, 2017). "Basal-like breast cancers are those which expressing both CK5/6 and EGFR, higher CK5/6 and EGFR expression demonstrated significantly more often central nervous system and lung recurrence but very rarely to the bones and liver." (PMID 29108347, 2017).
breast carcinoma (continued). "The therapeutic efficacy of a combinational therapy of EGFR-CAR-modified NK-92 cells and oncolytic herpes simplex virus 1 was also tested in a mouse model with breast cancer brain metastases." (PMID 29423418, 2017). "While high levels of HER2 in cancer cells can give rise to homodimers that activate signaling, heterodimers between HER2 and EGFR (ErbB1/HER1) or HER2 and ErbB3/HER3 appear to be particularly important in breast cancer." (PMID 28369073, 2017). "The results from testing the SMKI plus CAT-SKL antioxidant combination on a set of molecularly diverse breast cancer-derived cell lines suggest that the treatment strategy could be of substantive benefit to patients if developed as a molecularly targeted therapy for TNBC that overexpresses EGFR." (PMID 28281569, 2017). "Similar results have been shown for other mAbs anti-EGFR such as: cetuximab using HNSCC cells and trastuzumab in breast carcinoma bearing-mice." (PMID 28674498, 2017). "The use of EGFR TKIs or anti-EGFR mAbs for patients with NSCLC, CRC, pancreatic cancer, breast cancer, and SCCHN has improved patient prognosis in recent decades." (PMID 29140271, 2017). "Taken together, these results demonstrated that dimerization of EGFR and HER2 activates the JAK2/STAT1 signaling axis and induces ACTA2 expression in breast cancer cells." (PMID 28881584, 2017). "MDA-MB-231 cells were treated with three concentrations of the reversible EGFR inhibitors gefitinib and erlotinib based on published IC50 values for breast cancer cell lines in combination with 5μM JNK-IN-8." (PMID 29285221, 2017). "Activation of tyrosine kinase receptors from the human epidermal growth factor receptor family, related with gene EGFR, HER2, HER3, HER4, plays a key role in the initiation and progression of breast cancer." (PMID 29137596, 2017). "Next, ASSIGN was used to estimate the activation of each GFRN member (AKT, BAD, EGFR, HER2, IGF1R, KRAS (G12V), and RAF1) in 1119 breast cancer patient samples from TCGA and 55 samples from the ICBP panel of breast cancer cell lines." (PMID 28446242, 2017). "We and others have shown the important role of EGFR and HER2 signaling in breast cancer brain metastasis (BCBM) formation." (PMID 28008153, 2017). "More specifically, TGFBR1 and FGFR1 in combination with highly expressed E2F1 induce the most invasive phenotype in bladder cancer, whereas in breast cancer, it is the combined action of TGFBR2, EGFR, and E2F1 that triggers high levels of invasiveness." (PMID 28775339, 2017). "This included six EGFR-expressing, TNBC-derived cell lines and two HER2-amplified breast cancer-derived cell lines." (PMID 28281569, 2017). "In conclusion, we demonstrated that dimerization of EGFR and HER2 induced ACTA2 expression through a JAK2/STAT1-dependent signaling pathway that triggers breast cancer cell motility." (PMID 28881584, 2017). "In this respect, EGFR/HER2 signaling has been shown to induce a PKCδ-dependent phosphorylation of ERRα, leading to its stabilization in various breast cancer cell lines." (PMID 29190800, 2017). "HER2 has no recognized ligands and heterodimers between HER2 and EGFR (ErbB1/HER1) or HER2 and ErbB3/HER3 are important in breast cancer." (PMID 28369073, 2017). "The MDA-MB-468 and BT474 cell lines are well characterized models for EGFR and HER2 overexpressing breast cancer, but form highly homogenous tumors with questionable relevance to human breast cancer." (PMID 28423644, 2017). "In breast cancer, phosphorylated JNK significantly correlates with EGFR expression, positivity for cytokeratins, and the triple negative phenotype." (PMID 29285221, 2017). "In this study, the distribution of two membrane proteins, EpCAM and epidermal growth factor receptor (EGFR), was observed in two types of living breast cancer cell lines, Michigan Cancer Foundation-7 (MCF-7) and MDA-MB-231." (PMID 29257118, 2017).
breast carcinoma (continued). "Based on these results, we propose that increased ACTA2 expression is important for cell invasion and migration in EGFR and HER2-positive breast cancer cell models." (PMID 28881584, 2017). "S100A7 can interact with HER2 signaling through distinct and specific phosphorylation of tyrosine resides of EGFR/HER2, Src and SHP2 in breast cancer cells." (PMID 28051137, 2017). "EGFR is a tyrosine kinase receptor that is overexpressed in many tumors such as HNSCC and breast cancer, and contributes to tumorigenesis." (PMID 28893247, 2017). "Our data indicate that ZNF516 is a transcription repressor and a potential suppressor of EGFR, adding to the understanding of EGFR-related breast carcinogenesis and supporting the pursuit of ZNF516 as a potential therapeutic target for breast cancer." (PMID 28947780, 2017). "Since our present study describes PHD2 as an important regulator of sustained EGFR activity and stability, we rather favor the idea of PHD2 promoting EGFR-driven pathogenesis in breast cancer." (PMID 28038470, 2017). "As shown, EGFR is highly expressed in different ERα- cell lines compared to ERα+ breast cancer cell lines however; CNR2 is highly expressed in both breast cancer subtypes." (PMID 27213582, 2017). "Epidermal growth factor (EGF) binds EGFR, while heregulin (HRG) binds HER3 and HER4, and all three receptors dimerize with HER2 as the preferred co-receptor in HER2+ breast cancer cells, thus increasing HER2 activity." (PMID 29088778, 2017). "We investigated the regulatory mechanism of ACTA2 expression in EGFR-positive and/or HER2-positive breast cancer cells." (PMID 28881584, 2017). "We report a direct correlation between PHD2 and EGFR expression levels in tumor biopsies of 313 patients and in MDA-MB-231 breast cancer cells." (PMID 28038470, 2017). "ADAM10 is also involved in EGFR and ERBB2 receptor shedding, thus demonstrating its critical role in breast cancer." (PMID 27888801, 2017). "We investigated the association between isoform expressions and sensitivity to lapatinib, a dual tyrosine kinase inhibitor, which interrupts the HER2/neu and epidermal growth factor receptor (EGFR) pathways, and is a FDA-approved drug for breast cancer." (PMID 29066719, 2017). "Western blot was used to detect expression levels of Src, phospho-Src, HER2, phospho-EGFR and phospho-HER2 in our panel of breast cancer cell lines and the results were compared with those of flow cytometry." (PMID 28638122, 2017). "We previously identified a class of compounds we termed Disulfide bond Disrupting Agents (DDAs) that selectively kill EGFR+ and HER2+ breast cancer cells in vitro and blocked the growth of HER2+ breast tumors in an animal model." (PMID 28423644, 2017). "The effect was examined using two mouse colon cancer cell lines, CT26 and MC38, a mouse breast cancer cell line, 4T1, expressing considerable levels of EGFR, and human colon cancer cells, SW620, expressing little EGFR." (PMID 28473665, 2017). "Here we report that ERRF also plays an important role in the response of ERBB2-positive breast cancer cells to lapatinib, a dual tyrosine kinase inhibitor that interrupts the ERBB2 and EGFR pathway." (PMID 28415602, 2017). "Several studies have confirmed the significant benefits of EGFR-targeted agents in several types of cancers, including NSCL, CRC, pancreatic cancer, breast cancer, and SCCHN." (PMID 29140271, 2017). "Estradiol is known to rapidly activate many signaling molecules, including insulin-like growth factor 1 receptor (IGF-IR), epidermal growth factor receptor (EGFR), and mitogen-activated protein kinase (MAPK) in breast cancer cells." (PMID 29104246, 2017). "In previous studies, we showed that EGFR- and HER2-driven pathways are frequently altered in brain metastases of breast cancer patients." (PMID 28008153, 2017).